GALNS (galactosamine (N-acetyl)-6-sulfatase)
Diseases named in the same sentence as GALNS in open-access papers (continued):
Sharing a sentence is not in itself a finding about the gene and the disease.
lysosomal storage disorder (46 papers, 2010 to 2026). "Mucopolysaccharidosis type IVA (MPSIVA) is a lysosomal storage disease (LSD) caused by deficiency of N-acetylgalactosamine-6-sulfate sulfatase (GALNS), which causes the accumulation of keratan sulphate (KS) and chondroitin sulphate (CS)." (PMID 41783940, 2026). "Mucopolysaccharidosis IVA (MPS IVA) is a lysosomal storage disease caused by biallelic variants in the N-acetylgalactosamine-6-sulfatase (GALNS) gene and is characterized by progressive and multi-system involvements, dominantly with skeletal deformities." (PMID 38831290, 2024). "Mucopolysaccharidosis IVA (MPS IVA) is an autosomal recessive lysosomal storage disorder resulting from a deficiency in the activity of the enzyme N-acetylgalactosamine-6-sulfate sulfatase (GALNS)." (PMID 38831290, 2024). "Mucopolysaccharidosis (MPS) type IVA is a rare lysosomal storage disorder caused by aberrations of the N-acetyl-galactosamine-6-sulfatase (GALNS) enzyme." (PMID 39039523, 2024). "Mucopolysaccharidosis IVA (Morquio syndrome A, MPS IVA) is an autosomal recessive lysosomal storage disorder caused due to biallelic variants in the N-acetylgalactoseamine-6-sulfate sulfatase (GALNS) gene." (PMID 35729508, 2022). "Mucopolysaccharidoses (MPS) type IVA is a lysosomal storage disease that mainly affects the skeletal system and is caused by a deficiency of the enzyme N-acetylgalactosamine-6-sulfatase (GALNS)." (PMID 36292628, 2022). "Mucopolysaccharidosis type IVA (MPS IVA) or Morquio Syndrome A (OMIM #253000) is an autosomal recessive lysosomal storage disorder caused by mutations in the GALNS gene, encoding N‐acetylglucosamine‐6‐sulfate sulfatase enzyme (EC 3.1.6.4)." (PMID 33728253, 2021). "Mucopolysaccharidosis type IVA (MPS IVA) is an autosomal recessive lysosomal storage disorder caused by mutations in the GALNS gene, which leads to deficient activity of N‐acetylglucosamine‐6‐sulfate sulfatase." (PMID 33728253, 2021). "Mucopolysaccharidosis IVA (MPS IVA, Morquio A disease, MIM#253000) is an autosomal recessive lysosomal storage disorder caused by a deficiency of N-acetylgalactosamine-6-sulfate sulfatase (GALNS)." (PMID 32183856, 2020). "Mucopolysaccharidosis IV A (MPS IV A, Morquio A disease) is a lysosomal storage disease (LSD) produced by mutations on N-acetylgalactosamine-6-sulfate sulfatase (GALNS)." (PMID 27378276, 2016). "Morquio A syndrome (mucopolysaccharidosis [MPS] IVA; OMIM 253000) is a rare autosomal recessive lysosomal storage disorder caused by a deficiency in the enzyme N-acetylgalactosamine-6-sulfatase (GALNS; EC 3.1.6.4)." (PMID 24810369, 2014). "Mucopolysaccharidosis (MPS) IVA (OMIM: 253000) is a genetic lysosomal storage disease (LSD) caused by a deficiency in the N-acetylgalactosamine-6-sulfatase (GALNS) enzyme that leads to the lysosomal accumulation of the glycosaminoglycans (GAGs) keratan sulfate (KS) and chondroitin 6-sulfate (C6S)." (PMID 40362571, 2025). "MPS-IVA is a lysosomal storage disorder caused by mutations in the GALNS gene (NM_000512.5), which leads to a deficiency of the enzyme N-acetyl-galactosamine-6-sulfate sulfatase (GALNS) and the accumulation of glycosaminoglycans (GAG) keratan sulfate and chondroitin 6-sulfate." (PMID 40980122, 2025). "Mucopolysaccharidosis IV A (MPS IVA) is a lysosomal disorder caused by mutations in the GALNS gene." (PMID 36057729, 2022). "Mucopolysaccharidosis IV-A or Morquio A disease (MIM #253000] is an autosomal recessive lysosomal storage disease caused by the deficiency of N-acetylgalactosamine-6-sulfatase (GALNS), the lysosomal enzyme responsible for the hydrolytic degradation of keratan sulfate and chondroitin-6-sulfate." (PMID 30305043, 2018). "Mucopolysaccharidosis type IVA (MPS IVA, Morquio A Syndrome) is an autosomal recessive lysosomal storage disease (LSD) caused by a deficiency in the enzyme N-acetylgalactosamine-6-sulfatase (GALNS) due to a mutation in the GALNS gene located on chromosome 16q24.3." (PMID 29159073, 2018).
lysosomal storage disorder (continued). "GALNS are enzymes that remove sulfate groups from the chondroitin 6-sulfate (C6S), a deficiency in GALNS leads to the accumulation of sulfated glycosaminoglycans, resulting in lysosomal storage diseases." (PMID 28245787, 2017). "The lysosomal enzyme N-acetylgalactosamine 6-sulfatase (GALNS) raised attention in relation to its important role in the field of lysosomal storage diseases and, more recently, due to its connection to cancer and neuropathic pain." (PMID 40430394, 2025). "Mucopolysaccharidosis (MPS) IVA is a bone-affecting lysosomal storage disease (LSD) caused by impaired degradation of the glycosaminoglycans (GAGs) keratan sulfate (KS) and chondroitin 6-sulfate (C6S) due to deficient N-acetylgalactosamine-6-sulfatase (GALNS) enzyme activity." (PMID 40362571, 2025).
Morquio A disease (24 papers, 2011 to 2026). "There are two types of Morquio syndrome: type A, due to deficiency of N-acetyl-galactosamine-6-sulfatase (GALNS), and type B, due to deficiency of beta-galactosidase (GLB1)." (PMID 41141144, 2025). "In MPS-IVA/B (Morquio syndrome), deficiency in the galactose 6 sulfate sulfatase (GALNS) and/or β-galactosidase impairs the further steps of KS catabolism, which results in abnormal KS and C6-S levels in tissues." (PMID 36979788, 2023). "The Morquio syndrome (MPS IV) can be caused by a mutation either in the N-acetylgalactosamine-6-sulfatase (GALNS) gene (MPS type IVA), or in the gene for galactosidase beta 1 (GLB1; MPS type IVB)." (PMID 37441579, 2023). "Morquio A disease is caused by alterations in the GALNS gene, resulting in deficient activity of the enzyme N-acetylgalactosamine-6-sulfatase (GALNS) and the subsequent accumulation of keratan sulfate and chondroitin-6-sulfate in lysosomes." (PMID 33266180, 2020). "The molecular basis of GALNS deficiency leading to the clinical symptoms of Morquio A disease is of particular interest because of its allelic heterogeneity, clinical variability, and the presence of the common mutation characteristic for each ethnic population." (PMID 21251309, 2011). "Mutations in the GALNS or GLB1 genes must be identified to differentiate between type A and type B Morquio syndrome." (PMID 41141144, 2025). "Mucopolysaccharidosis IV (MPS IV, Morquio syndrome) is another autosomal recessive MPS subtype, associated with pathogenic variants in GALNS and GLB1." (PMID 39940729, 2025). "Mucopolysaccharidosis type IV (Morquio syndrome) is determined by impairment of the enzymes galactosamine-6-sulfate sulfatase (GALNS) (MPS IVA OMIM#253000) or beta-galactosidase 1 (GLB1) (MPS IVB OMIM#253010), which are involved in the breakdown of keratan sulfate and chondroitin sulfate." (PMID 38425718, 2024). "These rats showed undetectable levels of GALNS activity in all tissues analyzed and, as early as at 1 month of age, presented persistently high KS content in liver and serum, as well as a reduction of tibial length, key features of Morquio A disease." (PMID 34504088, 2021). "Mutations in GUSB, CLN6, and PPT1 cause Sly disease, neuronal ceroid lipofuscinosis (CLN6), and neuronal ceroid lipofuscinosis (CLN1), respectively, whereas mutations in GALNS and NAGA cause Morquio A disease and Schindler disease/Kanzaki disease, respectively." (PMID 34867278, 2021). "Mucopolysaccharidosis IV (Morquio syndrome) is an autosomal recessive disease that is split into two different subtypes, MPS IVA and MPS IVB, with deficiency of N-acetylgalactosamine-6-sulfatase (GALNS) and β-galactosidase, respectively." (PMID 31540112, 2019). "Decreased or absent GALNS activity is associated with MPS IVA (Morquio syndrome; MIM #253000)." (PMID 39077064, 2024). "MPS IV, also referred to as Morquio syndrome, presents two subtypes: MPS IVA and MPS IVB, caused by the lack of N-acetylgalactosamine-6-sulfate sulfatase (GALNS; MIM 253,000) and β-galactosidase (GLB1; MIM 253,010) respectively." (PMID 34051828, 2021).
mucopolysaccharidosis (18 papers, 2011 to 2025). A group of autosomal recessive or X-linked inherited lysosomal storage disorders affecting the metabolism of mucopolysaccharides, resulting in the accumulation of mucopolysaccharides in the body. "Mucopolysaccharidosis (MPS IVA) is caused by pathogenic variations in the GALNS gene, leading to the accumulation of glycosaminoglycans in tissues and causing progressive skeletal lesions." (PMID 41614872, 2025). "For instance, MSCs and their EVs have shown potential in treating corneal diseases caused by Mucopolysaccharidoses by delivering the enzyme N-acetylgalactosamine-6-sulfate sulfatase (GALNS) to defective cells." (PMID 38111850, 2023). "GALNS gene mutations have been associated with Mucopolysaccharidosis." (PMID 24475022, 2014).
Multiple sulfatase deficiency (2 papers, 2014). "Additional biochemical investigation and/or genetic analysis should be performed to rule out potential false positives incurred by different diseases such as multiple sulfatase deficiency (MSD) or mucolipidosis II or III (ML II/III) where low GALNS activity may be present." (PMID 25404155, 2014).
prostate carcinoma (2 papers, 2017 to 2023). A carcinoma that arises from epithelial cells of the prostate gland. "In human prostate cancer tissues, the ARSB activity was reduced and the GALNS activity was increased, compared to normal prostate tissue." (PMID 29245974, 2017).
breast carcinoma (1 paper, 2019). "For the ’Galactosamine (N-Acetyl)-6-Sulfatase’ (GALNS) gene an effect of 17 β-estradiol on the expression of GALNS could be detected by qPCR experiments in a breast cancer cell line, which is a hint to a tumor association of GALNS." (PMID 31438847, 2019).
cystinosis (1 paper, 2022). Cystinosis is a metabolic disease characterized by an accumulation of cystine inside the lysosomes, causing damage in different organs and tissues, particularly in the kidneys and eyes. "EVs naturally contain lysosomal components including heparan-alpha-glucosaminide N-acetyltransferase (HGSNAT), beta-glucocerebrosidase (GBA), N-acetylgalactosamine-6-sulfate sulfatase (GALNS), cystinosis (CTNS), deficient in MPS III, Gaucher, MPS IVA, and Cystinosin respectively." (PMID 39697359, 2022).
galactosialidosis (1 paper, 2025). A lysosomal storage disease characterized by coarse facial features, macular ''cherry red spot'', and dysostosis multiplex. "In contrast, in MPS IIIC mouse brains, NEU1 was deficient but GLB1 was increased, and GALNS was only slightly reduced, as in the tissues of galactosialidosis CathAS190A-neo mice, consistent with high stability of mouse GLB1 and GALNS enzymes in the lysosome." (PMID 40540388, 2025).
Maroteaux-Lamy-Disease (1 paper, 2017). "Genetic mutations of these enzymes lead to the lysosomal storage disorders Mucopolysaccharidosis VI (Maroteaux-Lamy-Disease), in which there is genetic mutation of ARSB, or Mucopolysaccharidosis IVA (Morquio A), in which there is genetic mutation of GALNS." (PMID 29245974, 2017).
metastatic tumors (1 paper, 2014). "Indeed, in comparison with African Americans, where we find many mucin producing potentially metastatic tumors, 46% displayed GALNS gene amplification." (PMID 24475022, 2014).
Sanfilippo syndrome (1 paper, 2016). "In vitro studies have suggested that GALNS is inhibited by HS, and keratan sulfate, one of the substrates of GALNS, is increased in the serum of Sanfilippo animal models and humans with Sanfilippo syndrome." (PMID 27491071, 2016). "A recent report suggested that in Sanfilippo syndrome, the enzyme GALNS might be inhibited by HS and heparin resulting in secondary accumulation of keratan sulfate in humans." (PMID 27491071, 2016).
type 1 diabetes (1 paper, 2020). "Interestingly, all enzymes involved in keratan sulfate degradation (ie., GALNS, GLB1, GNS, HEXA, and HEXB) were elevated in urines from youths with type 1 diabetes, compared to non-diabetic youths." (PMID 32453760, 2020).
autosomal recessive disease (7 papers, 2016 to 2022). Autosomal recessive form of disease. "Mucopolysaccharidosis type IV-A (OMIM #253000) or Morquio syndrome type A or simply MPS IV A is an autosomal recessive disease caused by the deficiency of the lysosomal enzyme N-acetylgalactosamine-6-sulfate sulfatase (GALNS)." (PMID 28904929, 2017).
skeletal dysplasia (6 papers, 2021 to 2025). Any Mendelian diseases that affects growth and development of the skeleton. "Likewise, current animal models are extensively represented by mice lacking GALNS expression; however, it is well known that MPS IVA mice do not recapitulate the skeletal dysplasia observed in humans, making some comparisons difficult." (PMID 38003337, 2023).
cancer (5 papers, 2018 to 2025). A tumor composed of atypical neoplastic, often pleomorphic cells that invade other tissues. "So far, APRT and GALNS have not been described in connection with cancer or cancer‐associated molecular pathways." (PMID 30259648, 2018). "Studies increasingly show that GALNS might also contribute to cancer development." (PMID 37707658, 2023). "DCTN1, GALC and GALNS also are not known cancer genes in the COSMIC database." (PMID 38310436, 2023).
metabolic disorder (5 papers, 2013 to 2022). "Multivalent dendrimers decorated with the DAB exhibited a relevant multivalent effect toward the lysosomal enzyme N-acetylgalactosamine-6-sulfatase (GALNS), which is involved in a rare metabolic disorder." (PMID 36080188, 2022).
tumor (3 papers, 2019 to 2023). "The GALNS-knockdown cells formed significantly smaller tumor size compared to control cells, as measured in terms of both volume and weight." (PMID 37707658, 2023). "The low expression of GALNS protein was confirmed in the tumor tissues originating from the cells transfected with GALNS shRNA compared to that of the control group by immunohistochemistry." (PMID 37707658, 2023). "Hence, ARSB may act as a tumor suppressor and GALNS as a proto-oncogene due to their impact on chondroitin sulfation and inhibition of SHP2." (PMID 32595831, 2020). "GALNS is overexpressed in NPC tissues, and promotes tumor growth via the PI3K/AKT/mTOR signaling pathway." (PMID 37707658, 2023).
GALNS also shares sentences with these, for which no sentence is quoted: genetic disease (3 papers); Morquio B syndrome (2); Aarskog-Scott syndrome (1); abscess (1); corneal diseases (1); cutaneous melanoma (1); diabetes (1); dysostosis multiplex (1); Gaucher disease (1); growth deficiency (1); head and neck squamous cell carcinoma (1); Hennekam syndrome (1); Hurler disease (1); Intellectual disability (1); Kanzaki disease (1); Lysosomal disease (1); microcephaly (1); mucolipidosis II (1); mucopolysaccharidosis type 7 (1); nasopharyngeal carcinoma (1); neuronal ceroid lipofuscinosis (1); Niemann-Pick disease type C (1); Noonan syndrome (1); pancreatic adenocarcinoma (1); PCWH syndrome (1); Pectus carinatum (1); psychiatric disorder (1); Retinal dystrophies (1); retinopathy (1); Schindler disease (1).
A further 5 diseases each share a sentence with GALNS in 1 paper.